IL17A (interleukin 17A)
Diseases named in the same sentence as IL17A in open-access papers (continued):
Sharing a sentence is not in itself a finding about the gene and the disease.
pneumonia (continued). "Thus, ILC3s secrete IL-17A to clear infection during early stages and help in the resolution of the inflammation to prevent ALI during pneumonia." (PMID 32849610, 2020). "Our data showed that neonatal S. pneumoniae pneumonia can increase the infiltration of inflammatory cells, both in the lung tissues and in the BALF, along with releasing higher levels of the pro-inflammatory cytokines (IL-4, IL-5, IL-13, and IL-17A)." (PMID 30723734, 2019). "Correcting for co-morbidities and the APACHE II scores, and despite the small number of patients in this study, we showed that VAP patients had significantly lower IL-17A levels compared to non-VAP pneumonia patients." (PMID 31614857, 2019). "We have shown that levels of IL-17A are elevated in patients with ARDS, many of whom had pneumonia." (PMID 28806403, 2017). "Previously, we showed that Candida colonized ICU patients with and without pneumonia as well as healthy controls had lower serum IL-17A and kynurenine levels compared to patients with candidemia." (PMID 27206014, 2016). "In our CF mice with PA508 pneumonia, E2 increased protein levels in BAL fluid of TNFα and IL-6 (upstream stimulators of IL-17 production) and also increased mRNA levels in lung tissue of IL-23 and the isoforms IL-17A and IL-17F." (PMID 21118573, 2010). "In view of our finding that rMntC stimulation of rMntC-EPS30-vaccinated mice enhanced IL-17A and IFN-γ production in the spleen and lung cells, we considered the possibility that rMntC-EPS30-induced production of these cytokines promoted resistance to S. aureus-induced pneumonia." (PMID 34358191, 2021). "NLRC4 activation during Gram-negative bacterial (K. pneumoniae, P. aeruginosa) pneumonia proves beneficial to the host via producing IL-1β, IL-17A, and neutrophil chemoattractants (keratinocyte cell-derived chemokines, MIP-2, and LPS-induced CXC chemokines) in the lungs." (PMID 32849610, 2020). "Human pneumococcal-responding IL-17A responses have been demonstrated previously in peripheral blood and in adenoidal mono-nuclear cells but in our study we have examined the mucosal compartment where pneumonia becomes established – the lung, which has not been examined before." (PMID 23555269, 2013). "Although the concentrations of IL-13, IL-17A, MIP-1α/CCL3, PAI1, sCD14, IL-1β, CCL11/eotaxin, VEGF/VPF, and RANTES/CCL5 did not exhibit significant differences between the HIV and pneumonia and HIV-only groups, several reasons could explain this lack of disparity." (PMID 38251391, 2024).
Insulin resistance (128 papers, 2012 to 2026). Increased resistance towards insulin, that is, diminished effectiveness of insulin in reducing blood glucose levels. "In conclusion, epicardial adipose tissue and IL-17A may be associated with the development of insulin resistance, coronary atherosclerosis, and type 2 DM due to their proinflammatory properties among patients with metabolic syndrome." (PMID 30862094, 2019). "The cytokines they secrete, such as IL-17A and IL-22, promote insulin resistance and adipose tissue inflammation." (PMID 41427046, 2025). "and decreased abundance of Treponema, F. succinogenes, Christensenellaceae and F16, promoted the absorption of excess PA by regulating the expression of IL-17A and Cd36, leading to the LCFAs accumulation and insulin resistance." (PMID 40878918, 2025). "(I) Specific gut microbiota structure promoted the absorption of excess PA by regulating the expression of IL-17A and Cd36, leading to the LCFAs accumulation and insulin resistance." (PMID 40878918, 2025). "Prior human studies in MASLD have shown increased baseline IL-6, IL-17A and TGF-β1 which are associated with hepatic inflammation, insulin resistance, and fibrosis." (PMID 40869413, 2025). "For example, pro-inflammatory cytokines, including IL1β and IL17A, can induce sAT dysfunction, leading to poor lipid storage, insulin resistance and inflammation." (PMID 32599074, 2020). "Since the adipose tissue as a central organ in insulin resistance as well as adipokines, chemokines and cytokines such as IL-17A are involved in these mechanisms, the following chapter will summarize the underlying molecular mechanisms." (PMID 32010143, 2019). "In a recent Chinese study, an increase in dietary sodium increased insulin resistance and circulating IL-17A concentrations, and both were significantly attenuated following short-term supplementation of potassium intake." (PMID 31159504, 2019). "In this study, it was aimed to investigate the relationship between the epicardial adipose tissue thickness (EATT) and serum IL-17A level insulin resistance in metabolic syndrome patients." (PMID 30862094, 2019). "In this context, IL-17A could play a central role in inflammation, endothelial dysfunction, insulin resistance, and the consequent cardiometabolic burden of patients with PsA." (PMID 39342310, 2024). "Blocking of IL-17A signaling using an antibody against IL-17A ameliorated liver injury and HCC development; hence, IL-17A may serve as a valuable non-invasive marker for insulin resistance and the pathogenesis of MASH in obese patients." (PMID 38774646, 2024). "B cells have been reported to primarily contribute to inflammation and insulin resistance via induction of an inflammatory T cell ratio (reduced Treg cells and increased Th1/Th17 cells) and production of pro-inflammatory cytokines (e.g. IL-17A) in obese mice and also in obese human subjects." (PMID 26161548, 2015). "Specific future focus should be maintained not only on suppression of TNF-α signaling as a critical target in the onset of insulin resistance, but also on the putative protective roles of the COX-2-mediated or IL-17A-mediated pathways in metabolic disorders." (PMID 38672413, 2024). "The other important finding of our study was that there was a positive correlation between serum IL-17 A level and EATT and insulin resistance." (PMID 30862094, 2019). "According to our knowledge, our study is the first to scrutinize the relationship between IL-17A, EAT, and insulin resistance." (PMID 30862094, 2019). "Increased level of inflammatory cytokines, such as IFN-γ, IL-1β, IL17A, IL6, and TNF-α, is also related to insulin resistance, and increased anti-inflammatory cytokines can improve glucose metabolism which regulates insulin sensitivity." (PMID 29541033, 2018).
Insulin resistance (continued). "Conversely, lack of FGF21 expression increases interleukin-17A (IL-17A) production, insulin resistance, and inflammation by free fatty acid (FFA)-mediated induction of Toll-like 4 (TLR4) signaling in hepatocytes." (PMID 34440674, 2021).
colon carcinoma (123 papers, 2010 to 2025). "Elevated levels of IL‐17A‐producing cells in colon cancer patients have been associated with poor prognosis, potentially due to vascular endothelial growth factor expression." (PMID 40922413, 2025). "This study investigates the serum expression levels of interleukins IL-8, IL-17A, and IL-33 in patients with colon cancer, analyzing their association with tumor grade and depth of invasion." (PMID 40725273, 2025). "For instance, cefoxitin treatment resulted in complete clearance of enterotoxigenic Bacteroides fragilis, a microbe that causes IL17A-dependent colon tumors." (PMID 28018236, 2016). "In our previous studies, we showed that the IL17A G197A, IL17Frs763780 and IL23Rrs10889677 polymorphisms are associated with the tumor location, especially with colon cancer." (PMID 26083022, 2015). "IL-17A is a pro-inflammatory cytokine primarily produced by Th17 cells whose elevated expression has been associated with an excessive inflammatory state and tumor growth in prostate and colon cancers." (PMID 37108754, 2023). "Furthermore, IL-17A-deficient mice exhibited enhanced tumor growth and lung metastasis in murine colon cancer and melanoma models." (PMID 34885241, 2021). "Finally, chemotherapy (for example, FOLFOX) is known to increase the expression of IL-17A, and an IL-17A neutralizing antibody has been shown to enhance the therapeutic responsiveness of established colon tumors, which are associated with high MMP-9 activity." (PMID 29983876, 2018). "IL-17A has been found with various functions in different tumors and may play a pathogenic role in colon cancer development." (PMID 22509371, 2012). "To further define the role of key TH17 cytokines in inhibiting chemokine expression, we treated human epithelial colon cancer cells (HCT116) with recombinant IL-17A and IL-22 and then determined the chemokine expression after DSS treatment." (PMID 40749055, 2025). "These mice showed larger colonic tumor size and increased intestinal cell proliferation and inflammation (e.g., increased mRNA expression of IL-17A and higher number of Ly6G + neutrophils) compared to water-treated ApcMin/+ control mice." (PMID 40022152, 2025). "As far as we know, this is the first study to investigate circulating IL8 and IL17A correlations in colon cancer." (PMID 38398137, 2024). "Th17 cells secrete IL-17A, which induces pyroptosis in colon cancer cells by stimulating the production of reactive oxygen species (ROS)." (PMID 39408824, 2024). "This study revealed the associations between serum levels of IL8, IL17A, and IL33 and colon cancer stages, as well as the correlations between these interleukins in healthy and cancer groups." (PMID 38398137, 2024). "IL-17A neutralization restores responsiveness to chemotherapy in colon cancer and resensitizes cells to cytotoxic treatments." (PMID 34299314, 2021). "Blockade of IL-17 with an IL-17A-blocking antibody significantly reduced ETBF-induced colonic tumor formation in Min mice." (PMID 33578830, 2021). "PEA reduces inflammation in human colonic tissue (from patients with IBD, colon cancer and appendicitis), including levels of IL-6, IL-8, IL-17A, MCP-1, and GM-CSF." (PMID 34916909, 2021). "In a mouse xenograft model with CT26 murine colon cancer cells, IL-17A-overexpressing cells presented significantly higher tumor growth than mock vector-treated cells." (PMID 33578830, 2021). "There was a significant accumulation of CXCR4-expressing MDSCs around colonic tumours (50- to 100-fold), along with increased expression of pro-tumorigenic cytokines IL-17A and IL-1β, in Tff2-null and wild-type mice compared with CD2–Tff2 mice." (PMID 26841680, 2016). "In humans, IL-17A expression has been reported in several tumor types, including ovarian cancer, prostate cancer, colon cancer, non–small cell lung cancer, hepatocellular carcinoma, gastric cancer and esophageal cancer." (PMID 23372655, 2013). "Therefore, IL-17A may play a pathogenic role in colon cancer." (PMID 22509371, 2012).
colon carcinoma (continued). "It was also reported that over-expression IL-17A in colon cancer cell lines promoted tumor growth in mice." (PMID 22509371, 2012). "In addition, we observed a reduction in IL‐17A and IL‐4 levels but increased IFN‐γ RNAm levels in the colonic tumors of the Mgl1−/− mice; IL‐17A and IL‐4 are cytokines supporting colon tumor growth, whereas IFN‐γ has antitumorigenic functions." (PMID 40033767, 2025). "In addition, decreased expression of RORC and IL17A correlates with worse prognosis in colon cancers." (PMID 39669566, 2024). "Notably, the addition of recombinant IL-17 A neutralizing antibody to the co-culture system impeded the inductive effect of IL-17-producing Tregs on colon cancer-initiating cell differentiation." (PMID 38317142, 2024). "Interleukin 17A is widely known to be a promoter of colon cancer initiation and progression." (PMID 38398137, 2024). "IL17A, for instance, is a potent proinflammatory cytokine that contributes significantly to the formation, growth, and metastasis of a wide range of malignancies, including colon cancer." (PMID 38398137, 2024). "However, inhibition of IL-17A in mice bearing KRAS-mutant lung tumors or transplantable colon cancer cell lines has provided proof-of-principle that targeting IL-17A in combination with anti–PD-1 is a viable strategy for controlling tumor growth." (PMID 36480166, 2023). "In addition, the serum level of IL-17A, an inflammatory factor that promoted the growth and metastasis of colon cancer, was also significantly decreased in LPC group." (PMID 36774343, 2023). "Similar to the differential microbiota results, systemic inflammatory cytokines were positively correlated with the colon cancer process, and key protein levels of LPS, IL-6, IL-22 and IL-17A in mouse serum were significantly higher after modelling than in the sham group (p < 0.01 or p < 0.01)." (PMID 34531745, 2021). "Moreover, there was also a decrease in levels of inflammatory cytokines TNF-α, IL-1β, IL-6, and IL-17A in the sera or colon tissues of Trim27−/− mice, which was consistent with the decreased inflammatory cell infiltrations in colon tumors of Trim27−/− mice." (PMID 30143645, 2018). "In addition, IL-17a was reported to facilitate colon cancer development, promoting cancer-elicited inflammation and preventing cancer cells from immune surveillance." (PMID 28147310, 2017). "However, another report using MC38 colon cancer cell lines showed that IL-17A inhibited tumor growth through antitumor immunity." (PMID 23372655, 2013). "Additionally, Treg that expand in adenomatous polyps of colon cancer start to produce IL-17A, which results in simultaneous immunosuppression of T helper function, while promoting tumor progression through inflammation-driven mastocytosis." (PMID 21060663, 2010). "TNFRSF11B may correlate with IL17A in the regulation of the colon cancer immune response." (PMID 34938284, 2021). "Together, these data indicate that expression levels of the MAIT17 signature gene IL17A and a positive MAIT17 regulator RORC positively correlate with prognosis of colon cancers." (PMID 39669566, 2024). "The study of colon cancer has been significantly enriched by the understanding of the roles of specific interleukins, particularly IL8, IL17A, and IL33." (PMID 38398137, 2024). "The levels of IL17A and IL8, two cytokines involved in inflammation, vary across the four stages of colon cancer." (PMID 38398137, 2024). "This study aimed to evaluate the serum levels of IL8, IL17A, and IL33 and their correlations with different stages of colon cancer." (PMID 38398137, 2024). "The highest concentration of IL17A and IL33 was in the 60–69 age group of colon cancer subjects, with significant difference in these IL concentrations between the 60–69 age group and the other age groups." (PMID 38398137, 2024).
colon carcinoma (continued). "This research investigated the serum levels of three interleukins (IL8, IL17A, and IL33) and the possible relationships between them in healthy people and colon cancer patients at different stages." (PMID 38398137, 2024). "Regarding the effect of TGFβ on colon tumor-infiltrating CD4+ T cells, the increased presence of TGFβ in sporadic colon tumors was obviously accompanied by the augmented presence of IL-17A+ IL-22+ CD4+ T cells." (PMID 36428508, 2022). "Indeed, we found that IL17A as a wild type genotype could protect against colon cancer unlike mutated genotype that could increase the susceptibility of colon cancer." (PMID 26083022, 2015). "In our study, IL8 and IL17A were found to be higher in the cancer group, while IL33 concentration was higher in the control group, reinforcing the fact that inflammatory cytokines and colon cancer are correlated." (PMID 38398137, 2024). "We also observed a correlation between IL8 and IL17A, one determining the other’s response, in different stages of colon cancer, but no other correlations have been observed between other interleukins in the four stages of this malignancy." (PMID 38398137, 2024). "The expression of IL-17 increases in the premalignant stage of CRC and directly correlates with dysplasia in the colonic adenoma-to-carcinoma sequence, making IL-17 a potential biomarker for colon cancer diagnosis and severity." (PMID 37211606, 2023). "Additionally, after being treated with IL-17A, an increasing number of CD8 + T cells showed in mouse-derived allograft colon cancer models." (PMID 37211606, 2023). "IL-17A binds to its type A receptor (IL-17RA), with several studies showing that IL-17A and IL-17RA expression is higher in colon tumor than in normal colon tissues." (PMID 35991881, 2022). "On the other hand, IL-17a showed increased levels in IL-17F over-expression HCT116 cells and decreased levels in the colon tissues of AOM-DSS treated il-17f−/− mice, suggesting a compensatory regulation of IL-17F and IL-17A gene expressions in colon cancer." (PMID 22509371, 2012). "In cancer patients, we observed a weaker correlation between IL8 and IL17A; however, there is a square correlation to be noticed between IL17A and IL33 (this study leaning to a direct response of circulating IL33 to IL17A variations in colon cancer development)." (PMID 38398137, 2024).